LINC01602 (long independently transcribed non-coding RNA 1602)
Synonyms: T1560
Gene: Long non-coding RNA gene on chromosome 8 (57,855,411 to 57,984,126, forward strand). Ensembl gene ENSG00000205293.
Diseases named in the same sentence as LINC01602 in open-access papers:
LINC01602 is named in the same sentence as 1 disease in open-access papers, as found by Europe PMC text mining. Sharing a sentence is not in itself a finding about the gene and the disease.
LINC01602 shares sentences with these, for which no sentence is quoted: rectal adenocarcinoma (1 paper).